NID2 (nidogen 2)
Description:
Cell adhesion glycoprotein which is widely distributed in basement membranes. Binds to collagens I and IV, to perlecan and to laminin 1. Does not bind fibulins. It probably has a role in cell-extracellular matrix interactions.
Synonyms: NID-2
Tractability: Antibody: its Gene Ontology location is reachable by antibodies, with high confidence; UniProt places it where antibodies can reach, with medium confidence; UniProt predicts a signal peptide or a membrane-spanning region; the Human Protein Atlas places it where antibodies can reach.
Gene: Protein-coding gene on chromosome 14 (52,004,809 to 52,069,059, reverse strand). Ensembl gene ENSG00000087303.
Subcellular location: Secreted, extracellular space, extracellular matrix, basement membrane
Subcellular location (Human Protein Atlas): Plasma membrane; Predicted to be secreted
Pathways (Reactome):
Extracellular matrix organization: Laminin interactions
Gene Ontology:
Molecular function: protein binding; collagen binding; extracellular matrix structural constituent; calcium ion binding
Biological process: basement membrane organization; cell adhesion; cell-matrix adhesion
Cellular component: basement membrane; extracellular exosome; extracellular matrix; plasma membrane; extracellular region
Genetic constraint (gnomAD): Loss-of-function variants: 73 observed, 138.07 expected, observed/expected ratio (o/e) 0.53, 90% interval 0.44 to 0.64. The upper end of that interval is the gene's LOEUF score, 0.64, which puts it in group 2 of 6, group 1 being the genes least tolerant of losing a copy. Missense variants: 1,748 observed, 1,788.6 expected, observed/expected ratio (o/e) 0.98, 90% interval 0.94 to 1.02. Synonymous variants: 722 observed, 713.89 expected, observed/expected ratio (o/e) 1.01, 90% interval 0.95 to 1.08.
Homologues: Orthologues: chimpanzee NID2 (99% identical), macaque NID2 (97% identical), dog NID2 (83% identical), pig NID2 (82% identical), mouse Nid2 (81% identical), rat Nid2 (80% identical), guinea pig NID2 (74% identical), rabbit NID2 (70% identical), tropical clawed frog nid2 (59% identical), zebrafish nid2a (50% identical), zebrafish nid2b (38% identical), Drosophila melanogaster arr (9% identical). Paralogues in human: NID1 (39% identical), LRP1 (19% identical), LRP1B (18% identical), LRP2 (17% identical), LRP8 (12% identical), EGF (12% identical), VLDLR (12% identical), LRP4 (12% identical), LRP5 (10% identical), LRP6 (10% identical), LRP3 (8% identical), and 2 more.
Diseases named in the same sentence as NID2 in open-access papers:
NID2 is named in the same sentence as 63 diseases in open-access papers, as found by Europe PMC text mining. Sharing a sentence is not in itself a finding about the gene and the disease. The quoted sentences say what the papers report.
breast carcinoma (9 papers, 2012 to 2025). "NID2 (Nidogen-2) is a basement membrane protein primarily produced by mesenchymal cells that has been linked to mesenchymal/de-differentiated phenotypes in breast cancer and melanoma." (PMID 32370304, 2020). "In cancer, high NID2 expression has previously been associated with several solid malignancies including gastric cancer, esophageal squamous cell carcinoma, ovarian cancer, melanoma, and breast cancer, although its causal role in pancreatic cancer and fibrosis progression remains unexplored." (PMID 38959305, 2024). "In this study, we have identified high frequencies of cancer specific abnormal hypermethylation of the parts of promoter regions of integrin ITGA1, ITGA4, ITGA9, and nidogen NID1, NID2 genes in breast cancer." (PMID 33500458, 2021). "Thus far, several studies have highlighted the utility of NID2 as a molecular or serum biomarker for several malignancies including gastric cancer, esophageal squamous cell carcinoma, ovarian cancer, melanoma, and breast cancer." (PMID 38959305, 2024). "NID2 gene expression is elevated in 9 of 24 cancer types, including GBM, lung adenocarcinoma, colon adenocarcinoma, breast cancer, and renal clear cell carcinoma (p < 0.001)." (PMID 40332526, 2025). "We furthermore detected Nidogen-2-positive stromal cells in tumors from orthotopic transplantation models, including the murine cell lines 4T1 and EO771 as well as the human breast cancer cell line MDA-MB-231." (PMID 30514914, 2018). "We were able to show that FXYD3 and PTX3 expression is associated with poor overall patient survival in SCC patients and LAD1, SLC7A5, SLPI, NID2, SPOCK1 and SULF1 correlated significantly with impaired pCR in breast cancer patients." (PMID 23251436, 2012). "From the upregulated genes of the EMT-core gene list, high PTX3 expression tends to poor overall survival of SCC patients (p = 0.16) and high expression of NID2 (p = 0.0091), SPOCK1 (p = 0.038) and SULF1 (p = 0.00029) significantly correlated with impaired pCR of breast cancer patients." (PMID 23251436, 2012).
gastric cancer (8 papers, 2007 to 2025). A primary or metastatic malignant neoplasm involving the stomach. "Increased NID2 expression also correlated significantly with overall survival in gastric cancer patients." (PMID 35216235, 2022). "In vitro experiments suggest that NID2 promotes invasiveness and migration in gastric carcinoma-derived tumor cells, where it was significantly overexpressed compared to healthy tissues." (PMID 35216235, 2022). "Previous studies have revealed that NID2 is overexpressed in gastric cancer and can boost gastric cancer cell invasion." (PMID 34604236, 2021). "The levels of Nidogen-2 were reported to be significantly increased in gastric cancer tissues in comparison with normal controls and positively associated with TNM stage and poor prognosis of gastric cancer patients." (PMID 32046329, 2020). "For the NID2 gene, we detected promoter methylation in 29% (14/48) of the colon and 95% (19/20) of the gastric carcinoma samples." (PMID 17328794, 2007). "NID2 promoter was methylated in 29% of colon and 95% of gastric cancers." (PMID 17328794, 2007).
bladder cancer (5 papers, 2019 to 2025). "The CCK-8 assay results showed that after knockdown of NID2, the proliferation ability of cancer cells was significantly weakened, indicating that NID2 has a promoting effect on the proliferation of bladder cancer cells (P< 0.0001)." (PMID 40948763, 2025). "For different cell lines, the RT-qPCR results showed that the mRNA expression level of NID2 was at a high level in all four human bladder cancer cell lines, and was significantly upregulated in the SW-1710 and BC-3C cell lines (P< 0.01)." (PMID 40948763, 2025). "NID2 plays a role in promoting proliferation in bladder cancer and evaluate in diffuse large B-cell lymphoma." (PMID 40948763, 2025). "Through RT-qPCR, CCK8 and other experiments, we verified the role of NID2 in bladder cancer." (PMID 40948763, 2025). "This study, for the first time, systematically revealed the pro-cancer function of NID2 in bladder cancer models: it showed significant mRNA high expression in bladder cancer cells, and after specific knockdown by siRNA, the cell proliferation ability was significantly inhibited." (PMID 40948763, 2025). "Finally, the wet experiment results confirmed that NID2 promotes the proliferation and migration of bladder cancer cells, inhibits apoptosis, and plays a pro-cancer role." (PMID 40948763, 2025). "Hypermethylation of individual biomarkers TWIST1, hTERT, NID2, and VIM was detected with a sensitivity of 92%, 97%, 84%, and 83%, respectively, and a specificity of 100% for each using urine sediment samples in Moroccan bladder cancer patients." (PMID 40141826, 2025). "Genes such as COL5A2, SVEP1, NID2, and MMP23B were responsible for the growth of many cancer types such as bladder cancer and mammary adenocarcinoma, but these genes may be involved in the pathogenesis of GBM." (PMID 31137733, 2019).
lung carcinoma (5 papers, 2013 to 2025). "Gene nidogen-2 (NID2) has been found to be associated with lung cancer." (PMID 30397551, 2018). "NID2, when demethylated or overexpressed in lung cancer cells, leads to decreased cell viability, proliferation, migration, and invasion, suggesting its role in promoting cancer development." (PMID 39968416, 2025). "Six DMRs located on HOXA9, HOXD3, PCDH17, NID2, NPTX2, and SFRP2 genes exhibiting clinical accuracy over 75% irrespective of lung cancer subtype and cancer progression stages were selected as lung cancer-specific exosome DNA methylation biomarkers." (PMID 39123492, 2024). "Of the 42 common Significant hypermethylated genes unique to Stages I and III, GALR1, NID2 have been identified as highly methylated in NSCLC, PAX7 has been identified in lung cancer but not reported with methylation, though PAX family genes have been previously reported being methylated in cancer." (PMID 24369052, 2013).
melanoma (5 papers, 2016 to 2025). A malignant, usually aggressive tumor composed of atypical, neoplastic melanocytes. "Loss of nidogen-2 has been associated with increased lung metastasis of B16 melanoma model when injected intravenously." (PMID 41181108, 2025). "High NID2 has also been associated with promoting an immunosuppressive microenvironment in melanoma, leading to poor response to checkpoint inhibitors." (PMID 38959305, 2024). "Previous study showed that NID2-deficient mice have a higher lung metastasis frequency, when intravenously injected with melanoma cells." (PMID 27793011, 2016). "Furthermore, a functional study revealed that NID2-deficient mice have higher lung metastasis upon tail vein injection of melanoma cells, suggesting a critical role of NID2 in suppressing the metastatic potential of cancer cells." (PMID 27793011, 2016).
ovarian carcinoma (5 papers, 2013 to 2025). A malignant neoplasm originating from the surface ovarian epithelium. "Among these molecules, several have been shown to be relevant to ovarian cancer and proposed as biomarkers, including NID-2 and VCAN." (PMID 33019700, 2020). "Several studies have shown promising results that high serum NID2 level could serve as a predictive marker for higher-stage ovarian cancer, particularly the serous type." (PMID 40332526, 2025). "Several groups have provided evidence that serum NID2 levels could serve as a potential ovarian cancer screening marker and higher serum levels of NID2 were correlated with higher disease stages." (PMID 40332526, 2025). "Also, the NID2 is reported to be a biomarker for ovarian cancer and has been reported to be closely correlated with CA125." (PMID 24565108, 2013).
breast tumors (3 papers, 2021 to 2024). "Abnormal hypermethylation of the NID2 promoter associated with suppression of its expression is known in aggressive types of breast tumors." (PMID 35216235, 2022). "Furthermore, in a scRNA-seq study of mammary specific polyomavirus middle T antigen overexpression mouse model (MMTV-PyMT) breast tumors by Bartoschek and colleagues, NID2 was identified as a marker of vascular CAFs, which may be linked to the expression of NID2 at vascular BMs." (PMID 38959305, 2024).
esophageal squamous cell carcinoma (3 papers, 2016 to 2024). Esophageal squamous cell carcinoma (ESCC) is a type of esophageal carcinoma (EC) that can affect any part of the esophagus, but is usually located in the upper or middle third. "Previous studies have associated NID2 expression with various cancers, including gastric, ovarian, bladder, pancreatic, and esophageal squamous cell carcinoma." (PMID 39684493, 2024). "The aim of the study is to analyze the functional roles of NID2 in the pathogenesis of nasopharyngeal carcinoma (NPC) and esophageal squamous cell carcinoma (ESCC)." (PMID 27793011, 2016).
Stroke (3 papers, 2012 to 2020). Sudden impairment of blood flow to a part of the brain due to occlusion or rupture of an artery to the brain. "NID2 encodes nidogen, an ECM glycoprotein and a major component of basement membranes and is recognized as having a role in post-stroke angiogenesis." (PMID 33293549, 2020). "However, one third of the genes were increased with suboptimal timing in aged rats, either on day 3 post-stroke (Adam17, Gpc3, Mmp14, Nid2, Tagln, Wnt5b) or on day 14 after stroke (Col4a2, Col8a1, Cthrc1, Cxcl1, Gpc3, Tgfbr2)." (PMID 23251410, 2012).
hearing loss (2 papers, 2020 to 2024). "NID2, identified in previous hearing loss GWAS, binds to collagens I and IV in the basement membrane." (PMID 38242899, 2024).
oral cancer (2 papers, 2020). "In esophageal, lung, bladder and oral cancers, NID2 methylation and reduced tissue expression are observed, suggesting biomarker context of NID2 may diverge in tumor tissue and EV compartments." (PMID 32370304, 2020). "Therefore, the assessment of methylation status in NID2 was a potential OSCC screening method that could be used to detect oral cancer in sample collected from invasive method such as oral rinse and swab approaches." (PMID 32171289, 2020).
aortic atherosclerosis (1 paper, 2024). A atherosclerosis that involves the aorta. "In line with our hepatic lipid metabolism studies, NID2 overexpression aggravated aortic atherosclerosis progression in male mice, suggesting a pivotal role of NID2 in atherogenesis." (PMID 39684493, 2024).
atherosclerosis (1 paper, 2024). A disease characterized by the build-up of fatty material and calcium deposition in the arterial wall resulting in partial or complete occlusion of the arterial lumen. "Additionally, reduced hepatic cholesterol efflux capacity in individuals with NAFLD has been linked to the presence of subclinical atherosclerosis, hinting that NID2 overexpression in hepatocytes may suppress cholesterol efflux, thereby leading to increased atherosclerosis." (PMID 39684493, 2024). "To investigate the molecular mechanisms by which NID2 regulates hepatosteatosis and atherosclerosis, we examined the expression of various proteins and genes involved lipid metabolism." (PMID 39684493, 2024). "Collectively, these findings suggest that NID2 contributes to the progression of both hepatosteatosis and atherosclerosis." (PMID 39684493, 2024). "In conclusion, the present study, for the first time, demonstrates the detrimental role of NID2 in hepatosteatosis and atherosclerosis." (PMID 39684493, 2024). "In this study, we investigated the role of NID2 in the pathogenesis of NAFLD and atherosclerosis by overexpressing NID2 using an adeno-associated viral (AAV) vector in Apoe−/− mice and Western diet feeding." (PMID 39684493, 2024). "NID2 overexpression in male Apoe−/− mice promoted hepatic steatosis, fibrosis, and atherosclerosis development." (PMID 39684493, 2024). "Our experiments revealed that NID2 overexpression leads to increased hepatosteatosis and atherosclerosis." (PMID 39684493, 2024). "Future studies are warranted to discover the other potential receptors of NID2 and investigate atherosclerosis in mice with cell-specific Lgr4 deletion combined with NID2 overexpression to clarify the role of the NID2-LGR4 axis in atherogenesis." (PMID 39684493, 2024). "To explore the effects of dysregulated hepatic metabolism on the development of atherosclerosis, we investigated atherosclerotic lesion formation in control and NID2-overexpressing Apoe−/− mice." (PMID 39684493, 2024). "In conclusion, these findings suggest that NID2 plays a deleterious role in both hepatosteatosis and atherosclerosis, making it a potential therapeutic target for these conditions." (PMID 39684493, 2024). "Comparable atherosclerosis in female control and NID2-overexpressing mice suggests sex-specific responses and implies that factors such as hormonal differences or sex-specific gene regulation modulate the effects of NID2 in atherosclerosis." (PMID 39684493, 2024). "En face ORO staining of whole aorta further confirmed a significant increase in atherosclerosis in male mice with NID2 overexpression [% plaque area: 12.5 ± 1.14 (74.09% increase)] compared with controls (7.18 ± 1.53), indicating a detrimental role for NID2 in the development of atherosclerosis." (PMID 39684493, 2024). "The presented results suggest that blocking NID2-induced signaling may serve as potential therapeutic approach to suppress both NAFLD and atherosclerosis." (PMID 39684493, 2024). "Therefore, we investigated the role of NID2 in regulating hepatosteatosis and atherosclerosis utilizing Western diet-fed Apoe−/− mice with/without NID2 overexpression." (PMID 39684493, 2024).
bladder tumors (1 paper, 2020). "Hence, a suitable impact was suggested, in particular for ECRG4, for discriminating BPH or urocystitis from bladder tumors, which is comparable with proposed biomarker candidates, like NID2 or TWIST1." (PMID 32046186, 2020).
cerebral amyloid angiopathy (1 paper, 2022). "NID2 is a pathogenic gene for neurological disease because the severity of cerebral amyloid angiopathy is least in the striatum, where NID2 is reduced." (PMID 35627223, 2022).
cholesteatoma (1 paper, 2014). A pathologic process characterized by the proliferation of keratinizing squamous epithelium resulting in the accumulation of keratin and cells in the middle ear and/or mastoid. "Neck of cholesteatoma and cholesteatoma sack showed very low levels of these proteins (NID2 showed more than 20-fold lower levels compared with the tympanic membrane and EACS)." (PMID 25093596, 2014).
coloboma (1 paper, 2024). An abnormality in which a part of a structure in one or both eyes is missing. "The conserved expression in the OFM across species and the coloboma phenotype observed in nid1 morphant zebrafish suggest an essential role for nidogen in optic fissure closure and further investigation of human orthologs NID1 and NID2 as novel candidate coloboma genes." (PMID 38821055, 2024).
endometriosis (1 paper, 2022). The growth of functional endometrial tissue in anatomic sites outside the uterine body. "Among the 15 DEPs, COL1A1, COL6A2, and NID2 are among the proteins with strong interactions, and MT2A, TYMP, COL1A1, and COL6A2 have already been associated with endometriosis." (PMID 36232817, 2022).
epithelial dysplasia (1 paper, 2020). "Because NID2 is a cell-adhesion protein on the basement membrane, NID2 methylation could lead to a loss of NID2 expression, resulting in a false negative detection in epithelial dysplasia or non-invasive cancerous lesion." (PMID 32171289, 2020).
esophageal cancer (1 paper, 2020). A primary or metastatic malignant neoplasm involving the esophagus. "Elevated serum NID2 has been reported in cases of ovarian and esophageal cancers." (PMID 32370304, 2020).